NPC2 (NPC intracellular cholesterol transporter 2)
Diseases named in the same sentence as NPC2 in open-access papers (continued):
Sharing a sentence is not in itself a finding about the gene and the disease.
Niemann-Pick disease type C (continued). "However, Niemann-Pick disease type C, a disease caused by mutations in the NPC1 and NPC2 genes, is accompanied by psychiatric symptoms – mainly psychotic, mood-related, and impulse control-related." (PMID 41044382, 2026). "A prime example is Niemann–Pick type C disease (NPCD), where cholesterol export from the endosomal–lysosomal system is impaired due to variants of either NPC intracellular cholesterol transporter 1 (NPC1) or NPC intracellular cholesterol transporter 2 (NPC2)." (PMID 40565243, 2025). "Niemann–Pick type C disease (NPCD-MIM 257220; MIM607625) is an autosomal recessive neurovisceral lysosomal storage disorder due to mutations in the NPC1 (95% of patients) or NPC2 genes, encoding two proteins involved in the intracellular trafficking of cholesterol and other lipids." (PMID 34682919, 2021). "NPC-2 proteins were named because its identification is related to Niemann-Pick disease type C2." (PMID 32868841, 2020). "Hypomyelination in the central nerves system (CNS) is one of the most obviously pathological features in Niemann-Pick Type C disease (NPC), which is a rare neurodegenerative disorder caused by mutations in the NPC intracellular cholesterol transporter 1 or 2 (Npc1 or Npc2)." (PMID 30866987, 2019). "In Niemann–Pick disease type C, an LSD with a wide clinical spectrum, a novel mutation was identified by whole exome sequencing in a proband of Asian origin, which was a deletion spanning two exons of Niemann–Pick disease type C2 (NPC2) gene." (PMID 31554517, 2019). "In addition, our genetic mutation rates in EOPSP are based on pathogenic mutations that are directly genotyped on the Illumina NeuroChip, and targeted NPC1 and NPC2 sequencing was limited to cases that had biochemical evidence of Niemann‐Pick type C disease." (PMID 31299107, 2019). "However, enhanced anxiety is observed in the patients with Niemann-Pick diseases, type C, which is characterized by sphingolipid accumulation in biological tissues and organs due to the mutations in the NPC1 or NPC2 genes." (PMID 31333574, 2019). "Similarly, Niemann-Pick disease type C (NPC) is caused by defects in cholesterol efflux from lysosomes due to mutations in genes coding for NPC1 and NPC2 proteins." (PMID 25949827, 2015). "Niemann-Pick disease type C (NP-C) is a devastating, neurovisceral lysosomal storage disorder which is characterised by variable manifestation of visceral signs, progressive neuropsychiatric deterioration and premature death, caused by mutations in the NPC1 and NPC2 genes." (PMID 25479233, 2014). "Niemann-Pick disease type C (NPC) is a genetic, rare, highly heterogeneous, and progressive lysosomal disorder characterized by the dysfunction of NPC1 or NPC2 proteins, which leads to the accumulation of multiple lipid species." (PMID 39061081, 2024). "For example, NPC1 (Niemann-Pick disease, type C1), a protein containing SSD, cooperates with a secreted protein NPC2 to transport cholesterol in lysosomes." (PMID 34115759, 2021). "This is demonstrated for varying glucose influx and for yeast cells lacking the sterol transporters Ncr1 and Npc2, a model for Niemann Pick type C disease in humans." (PMID 40603986, 2025). "For example, in NPC1 and NPC2, which cause Niemann-Pick disease type C, no NPC1 variants were identified in the WGS data from the 1495 individuals in the TWB, and only one NPC2 variant was identified." (PMID 37741878, 2023). "Niemann-Pick type C disease (NPC) is a rare inherited neurodegenerative disorder characterized by an accumulation of intracellular cholesterol within late endosomes and lysosomes due to NPC1 or NPC2 dysfunction." (PMID 34948052, 2021). "Walkley explains this using the example of Niemann-Pick type C disease, in which a lack of functional NPC1 or NPC2 proteins leads to impaired free cholesterol recycling in the endosome system." (PMID 39404425, 2024).
Niemann-Pick disease type C (continued). "The patient did not have a pattern of clinical deterioration to suggest Niemann-Pick Disease type C (NPC1 [MIM 257220] and NPC2 [607625]) but, given the gaze palsy, defects in NPC1 and NPC2 were excluded through single gene sequencing." (PMID 25885783, 2015).
lysosomal storage disorder (41 papers, 2010 to 2026). "Niemann–Pick type C (NPC) is a lysosomal storage disorder (LSD) caused by pathogenic variants in either the NPC1 or NPC2 genes, which encode proteins involved in the lysosomal export of unesterified cholesterol." (PMID 39596250, 2024). "Purkinje cell (PC) loss occurs at an early age in patients and animal models of Niemann-Pick Type C (NPC), a lysosomal storage disease caused by mutations in the Npc1 or Npc2 genes." (PMID 37024714, 2023). "Niemann–Pick type C (NP-C) disease is a rare lysosomal storage disease caused by mutations in NPC1 (95% cases) or NPC2 (5% cases)." (PMID 37440478, 2023). "NPC is a rare neurodegenerative lysosomal storage disorder caused by mutations in the NPC1 (95% of the cases) or NPC2 genes, which are involved in cholesterol trafficking." (PMID 33917666, 2021). "Niemann-Pick type C (NPC) disease is an autosomal recessive lysosomal storage disease that is caused by a mutation of the NPC1 or NPC2 gene, in which un-esterified cholesterol and sphingolipids accumulate mainly in the liver, spleen, and brain." (PMID 33986646, 2021). "Niemann-Pick type C (NPC) disease is an autosomal recessive lysosomal storage disorder caused by mutations in NPC1 or NPC2 genes." (PMID 32138288, 2020). "Mutations in NPC1 and NPC2 cause Niemann Pick type C, a lethal lysosomal storage disease characterised by lysosomal cholesterol accumulation in multiple organ systems." (PMID 33144569, 2020). "Niemann-Pick disease type C (NPC) is an autosomal recessive lysosomal storage disorder resulting from mutations in the NPC1 (95% of cases) or NPC2 genes." (PMID 30847690, 2019). "Niemann-Pick C disease (NPC) is an autosomal recessive lysosomal storage disorder resulting from mutations in the NPC1 (95% of cases) or NPC2 genes." (PMID 30847690, 2019). "NPC is a lysosomal storage disorder caused by the pathogenic deficiency of either the NPC1 or NPC2 gene." (PMID 30023294, 2018). "NPC disease is a progressive neurodegenerative lysosomal storage disease caused by mutations in either the NPC1 or NPC2 genes." (PMID 29119141, 2017). "Niemann-Pick type C (NPC) disease is a neurodegenerative lysosomal storage disease caused by mutations in either the NPC1 or NPC2 gene." (PMID 27019000, 2016). "Niemann Pick C [NPC-MIM 257220; MIM607625] disease is a neurodegenerative lysosomal storage disorder due to mutations in NPC1 or NPC2 genes." (PMID 25396745, 2014). "Niemann Pick C (NPC) disease is a neurovisceral lysosomal storage disorder due to mutations in NPC1 or NPC2 genes, characterized by the accumulation of endocytosed unesterified cholesterol, gangliosides and other lipids within the lysosomes/late endosomes." (PMID 23433359, 2013). "We investigated the possible role of rare sequence variants in the NPC1 and NPC2 genes, mutations in which are causative for the lysosomal storage disorder NPC, in three age-related neurodegenerative diseases (PD, FTLD, PSP)." (PMID 24386122, 2013). "At variance with the paucity of zebrafish models for the aSMase-deficient forms of NPD, various attempts have been made to model the type C form of NPD, a lysosomal storage disease distinct from sphingolipidoses that depends on cholesterol trafficking defects due to mutations in NPC1 or NPC2 genes." (PMID 36902174, 2023). "Mutations in NPC1 and NPC2 cause the lethal Niemann Pick type C (NPC) lysosomal storage disease." (PMID 33144569, 2020). "Niemann–Pick type C disease (NPC-MIM 257220; MIM607625) is an autosomal recessive lysosomal storage disorder due to mutations in NPC1 (95% of patients) or NPC2 genes, encoding two proteins involved in the intracellular trafficking of cholesterol and other lipids." (PMID 32138288, 2020). "Interestingly, the lysosomal storage disorder Niemann Pick’s disease is caused by a mutation in the cholesterol-transporting proteins NPC1 or NPC2, which results in the accumulation of cholesterol in lysosomes." (PMID 32365555, 2020).
lysosomal storage disorder (continued). "NPC2 plays roles in cholesterol and glycolipid trafficking and/or transport, and mutations in it are causally related to Niemann-Pick disease, a life-threatening lysosomal storage disease, but studies on its role in M. tuberculosis pathogenesis are scarce." (PMID 27826286, 2016). "Niemann-Pick type C (NPC) disease is a lysosomal storage disease (LSD) characterized by the buildup of endo-lysosomal cholesterol and glycosphingolipids due to loss of function mutations in the NPC1 and NPC2 genes." (PMID 37567876, 2023). "The Niemann Pick type C (NPC) proteins, NPC1 and NPC2, are involved in the lysosomal storage disease, NPC disease." (PMID 30181526, 2018). "Niemann-Pick C disease (NPC) is an autosomal recessive lysosomal storage disorder characterized by accumulation of unesterified cholesterol and other lipids within the lysosomes due to mutation in NPC1 or NPC2 genes." (PMID 25396745, 2014). "This notion is best illustrated by the severe progressive neurodegeneration in Niemann-Pick Type C (NPC) disease, one of the lysosomal storage diseases, caused by mutations in the NPC1 or NPC2 gene." (PMID 20386595, 2010). "Mutations in acid sphingomyelinase (aSMase), encoded by SMPD1, are causative of the NPD type A and B forms, whereas NPD type C, a lysosomal storage disease distinct from sphingolipidoses, is a cholesterol trafficking defect due to mutations in NPC1 or NPC2 genes." (PMID 36902174, 2023). "Finally, in addition to GRN, we found upregulation of other lysosomal genes frequently dysregulated in lysosomal storage disorders such as NEU1, NPC2, PSAP, CTSD, LAMP1, and HEXA." (PMID 38643236, 2024). "We have previously demonstrated that a lysosomal storage disorder Niemann-Pick type C (NPC), in which free cholesterol accumulates in late endosomes/lysosomes due to NPC1/NPC2 dysfunction, shows cholesterol-dependent accumulation of intracellular Alzheimer's Aβ and APP-CTF fragments." (PMID 27902765, 2016).
Niemann-Pick disease (14 papers, 2016 to 2025). A group of inherited, severe metabolic disorders in which sphingomyelin accumulates in lysosomes in cells. "The hypoactivity of CAR and ARI-treated fish aligns closely with the behavior shown by Npc2-deficient zebrafish used to model Niemann-Pick disease in humans." (PMID 40700140, 2025). "Niemann–Pick disease (NPC) is typically due to biallelic pathogenic variants in the NPC1 or NPC2 gene located on 18q11, with their encoded proteins having roles in the movement of lipids within cells." (PMID 38570878, 2024). "NPC1 and NPC2, the causative genes of Niemann–Pick disease, are responsible for the transport of free cholesterol in lysosomes." (PMID 38354786, 2024). "As only 5% of patients suffering from Niemann-Pick disease harbor a mutation in NPC2 and 95% harbor a mutation in NPC1, the knowledge regarding the pathophysiology of NP-C1 is much more extensive than that regarding NP-C2." (PMID 33924575, 2021). "Bovine homologs for the genes that cause Niemann-Pick disease in humans (SMPD1, NPC1 and NPC2), are located on BTA15, BTA24 and BTA10 respectively." (PMID 32970694, 2020).
lung carcinoma (9 papers, 2013 to 2024). "The presence of NPC2 protein in pleural effusions of lung adenocarcinoma suggests that it may be used as a potential diagnostic marker for lung cancer." (PMID 38001127, 2023). "Thus, higher NPC2 levels in peripheral blood might underlie immunopathological processes that are similar in active sarcoidosis and in TB, but are less common during the cessation of sarcoidosis symptoms, and even lower in lung cancer and pneumonia." (PMID 34685683, 2021). "Elevated serum levels of NPC2 have been observed in patients with lung cancer and, more recently, HCC." (PMID 26020769, 2015). "Comparison between these normal tissues (N) and their corresponding tumor tissues (T) was carried out and it was found that NPC2 was significantly up-regulated in breast, colon and lung cancers." (PMID 24147030, 2013). "The expression of NPC2 was found to be up-regulated in human breast, colon and lung cancers, while, in contrast, there was down-regulation of NPC2 expression in kidney and liver cancers." (PMID 24147030, 2013). "NPC2 can be secreted by early-stage lung cancers and influence the tumor microenvironment." (PMID 37920509, 2023). "The IHC staining showed that NPC2 expression was increased in breast, colon and lung cancers." (PMID 24147030, 2013). "Although it is not clear yet if NPC2 plays a role in lung adenocarcinoma, the presence of NPC2 protein in pleural effusion of patients with lung adenocarcinoma suggests that it may have a use as a potential diagnostic marker for lung cancer." (PMID 24147030, 2013). "Furthermore, we found that low expression of KCNE1, NPC2, and SFTPD promotes lung cancer cell proliferation and invasion and M2 macrophage polarization." (PMID 38509982, 2024). "To additionally validate the accuracy of the bioinformatics analysis findings, we first examined KCNE1 in normal Epithelial cells BEAS-2B and malignant epithelial cells (lung cancer cell lines, H1299, A549, and HCC827), NPC2, and the mRNA and protein expression of SFTPD." (PMID 38509982, 2024). "Together, these findings show that NPC2 secreted by premalignant lung tumours suppresses IMC recruitment to the microenvironment in a paracrine manner, thus identifying a novel target for the development of chemopreventive strategies in lung cancer." (PMID 26183450, 2015). "However, only NPC2 expression levels were significantly higher in TB than in the majority of the other lung diseases, such as non-active sarcoidosis (p = 0.021), lung cancer (p = 0.018), and pneumonia (p = 0.006)." (PMID 34685683, 2021). "In addition, NPC2 accurately distinguished TB from the clinically similar conditions pneumonia (AUROC, 0.88), non-active sarcoidosis (0.87), and lung cancer (0.86), but not from active sarcoidosis (0.66)." (PMID 34685683, 2021).
hepatocellular carcinoma (8 papers, 2013 to 2025). A malignant tumor that arises from hepatocytes. "In patients with hepatocellular carcinoma, NPC2 downregulation is associated with adverse clinicopathological features by regulating mitogen-activated protein kinase (MAPK)/extracellular signal-regulated kinase (ERK) activation." (PMID 40302802, 2025). "There have been many studies related to NPC2 in hepatocellular carcinoma, but very few studies have been conducted in gastric cancer." (PMID 40302802, 2025). "Previously, we reported that NPC2 expression was downregulated in human liver cirrhosis and hepatoma tissues." (PMID 29874879, 2018). "Previously, we conducted an immunohistochemical-based study to examine the expression of NPC2 in a variety of different human cancers, and meanwhile NPC2 was found to be down-regulated in human liver cirrhosis and hepatoma tissues." (PMID 27420058, 2016). "On the other hand, NPC2 was found to be down-regulated in renal cell carcinoma, liver cirrhosis and hepatoma tissues." (PMID 24147030, 2013). "In addition, dysregulation of sera NPC2 is associated with liver cirrhosis and hepatocellular carcinoma (HCC)." (PMID 24147030, 2013). "In addition, low expression of NPC2 in hepatocellular carcinoma tissues may indicate poor postoperative prognosis in hepatocellular carcinoma patients." (PMID 40302802, 2025). "Furthermore, low NPC2 levels may indicate a passive prognosis and contribute to procession of hepatocellular carcinoma by modulating of the ERK1/2 pathway." (PMID 38586328, 2024). "We previously provided evidence that the downregulation of NPC2 is correlated with the α-fetoprotein level, tumor type, vascular invasion, and pathology stages of hepatocellular carcinoma (HCC) patients." (PMID 29874879, 2018). "Four genes, CD14, NPC2, IER3, and GZMA, have been extensively investigated in hepatocellular carcinoma." (PMID 37354485, 2023).
lung adenocarcinoma (7 papers, 2013 to 2026). A carcinoma that arises from the lung and is characterized by the presence of malignant glandular epithelial cells. "The biological functions and mechanisms of NPC2 in lung adenocarcinoma were elucidated through both in vitro and in vivo experiments, which included CCK-8 assays, colony formation assays, flow cytometry, Transwell assays, and xenograft tumor models." (PMID 41624864, 2026). "NPC2 has been previously reported to be abundantly secreted by human and mouse lung adenocarcinoma cells." (PMID 26183450, 2015). "Although this previous study detected NPC2 secretion from human lung adenocarcinoma cell lines, it remains unclear if NPC2 secretion levels could be altered by the oncogenic mutation status and/or disease progression." (PMID 26183450, 2015). "Our findings showed that NPC2 is enhanced in lung adenocarcinoma tissue." (PMID 24147030, 2013).
Ataxia (6 papers, 2011 to 2024). Ataxia refers to impaired coordination of voluntary muscle movement. "All patients were tested with whole genome sequencing containing hereditary ataxia panels, which include NPC1 and NPC2 mutations and other genetic causes of ataxia." (PMID 38790666, 2024). "In contrast, the study from Tubingen, Germany, identifying patients by sequencing NPC1 and NPC2 detected six cases in 204 individuals with early-onset ataxia." (PMID 38790666, 2024). "NPC1 and NPC2 are currently included in gene panels for infantile cholestatic disease, early onset ataxia (EOA), dystonia, IEMs, organic psychosis, early-onset cognitive decline, hepatosplenomegaly, and developmental delay." (PMID 30665446, 2019). "Despite normal c-triol concentrations, a genetic analysis of NPC1 or NPC2 was performed, as these patients presented typical clinical symptoms, including ataxia, dysarthria, vertical supranuclear gaze palsy, dysphagia and psychosis." (PMID 26981555, 2016). "Although we noticed a tendency towards a cerebellar cholesterol reduction in the NPC2 treated animals, all of the NPC2−/− mice developed severe ataxia by the end of the treatment schedule." (PMID 22073306, 2011). "Our study showed that some adults with ataxia who were shown to have no mutations in NPC1 or NPC2, had high plasma concentrations of 3β,5α,6β-triOH-Gly." (PMID 38790666, 2024). "In a study of 96 patients with unexplained EOA (age at onset < 40 years), targeted high-throughput sequencing of 122 known ataxia genes including NPC1 and NPC2, NP-C diagnoses were confirmed in 2/96 patients (2.1%)." (PMID 30665446, 2019).